KRT7 (keratin 7)
Diseases named in the same sentence as KRT7 in open-access papers (continued):
Sharing a sentence is not in itself a finding about the gene and the disease.
breast tumors (17 papers, 2008 to 2025). "Strikingly, qPCR showed that KRT7 mRNA levels were increased by sevenfold and ninefold in the lung and breast tumors, respectively; meanwhile, the KRT7 downstream oncogenic forkhead box protein A1 (FOXA1) was markedly elevated." (PMID 37185462, 2023). "Western blots showed that KRT7 levels were significantly higher in the lung and breast tumor tissues than that in the adjacent normal tissues." (PMID 37185462, 2023). "In our cases, cytokeratin 7, TTF-1, p63, and p40 for lung tumors; CK7, GATA3, and GCDFP-15 for breast tumors; and cytokeratins, synaptophysin, chromogranin, and CD56 for neuroendocrine tumors were the most used markers." (PMID 35308701, 2022). "This revealed that both EPI (e.g. LLGL2, CLDN4, KRT7, ST14) and MES (e.g. SNAI1, VIM, AP1M1) genes positively correlated with PIEZO1 expression across all quintiles, whilst markers of luminal breast tumors (ESR1, FOXA1, PGR) negatively correlated in all instances." (PMID 38632473, 2024). "Most breast tumors will be positive for keratin 7 but negative for keratins 5/6, 17, and 20 which is very useful for distinguishing breast adenocarcimas from adenocarcinomas from other glandular sites." (PMID 18414623, 2008).
clear cell carcinoma (17 papers, 2008 to 2025). "Diagnosis of clear cell carcinoma was based on certain histological characteristics of the tumour and immunohistochemical analysis (PAS staining, keratins AE1/AE3, EMA, cytokeratin 7, cytokeratin 20, melanosomes, vimentin, Chromogranin, Synaptophysin, S-100, SMA)." (PMID 18442419, 2008). "Immunohistochemical analysis showed positive staining for carbonic anhydrase 9 (CA9) but negative staining for cytokeratin 7 (CK7), consistent with clear cell carcinoma originating from the kidney." (PMID 32347406, 2020).
clear cell renal cell carcinoma (16 papers, 2009 to 2025). "Interestingly, in clear cell renal cell carcinomas, the detection of KRT19 along with KRT7 was associated with better clinical outome." (PMID 36033462, 2022). "However, high KRT7 expression was associated with better OS in papillary renal cell carcinoma and the KRT7/KRT19 expressing subtype was associated with better outcomes in clear cell renal cell carcinoma." (PMID 34070214, 2021).
cervical carcinoma (15 papers, 2009 to 2025). A carcinoma arising from either the exocervical squamous epithelium or the endocervical glandular epithelium. "In line with our findings, strong immunostaining for KRT7 has been found in 90% of high-grade squamous intraepithelial lesions (HSIL or CIN2/3) and cervical carcinomas." (PMID 39712018, 2024). "KRT7 and KRT19 staining of lymph nodes is reported to have a potential in detecting micrometastatic foci in regional lymph nodes of patients with GBC and cervical cancer respectively." (PMID 37142981, 2023). "Furthermore, the expressions of S100P, S100A4, KRT7 and TGM2 were also induced by silencing of ACTL6A in cervical cancer cells." (PMID 34395295, 2021). "Cytokeratin-7, a protein that is present in cervical cancer but not normal stratified squamous epithelia, increased in E7-transduced cells, but decreased in E6-transduced cells." (PMID 19698150, 2009). "In summary, the majority of cervical cancers can be divided into two groups on the basis of molecular signatures: SCCs most probably originate from the KRT5+ squamous lineage of the ectocervix, whereas ADCs most probably originate from the KRT7+KRT8+ columnar lineage of the endocervix." (PMID 33462395, 2021). "Interestingly, Cytokeratin-7 is present in up to 87% of cervical cancers, whereas it is absent from other epithelial cancers." (PMID 19698150, 2009).
cyst (15 papers, 2009 to 2025). A sac-like closed membranous structure that may be empty or contain fluid or amorphous material. "Although cyst-like expansion of the tubules was unclear, tubular atrophy was dominantly found in the distal tubules by cytokeratin 7 (CK7) staining." (PMID 34246230, 2021). "Although cyst-like expansion of the tubules was unclear, tubular atrophy was dominantly found in the distal tubule by cytokeratin 7 staining." (PMID 34246230, 2021). "Immunohistologically, the epithelial lining of the cyst was diffusely positive for calretinin, and there was cytoplasmic positivity for cytokeratin 7 and calretinin, confirming mesothelial differentiation." (PMID 33000344, 2020). "The most consistent staining is seen with cytokeratin 7, strongly indicative of urethral origin of the cyst." (PMID 31301740, 2019). "After they were expanded, hepatic progenitor cell cultures could undergo differentiation into hepatocyte-like cells that expressed ALB and AAT and stored glycogen, or into cholangiocyte-like cells that formed duct-like cyst structures, expressed KRT7 and KRT19 and acquired epithelial polarity." (PMID 19649295, 2009). "Furthermore, immunohistochemical staining showed the cyst to be cytokeratin 7 (CK7) positive and cytokeratin 20 (CK20) and CDX2 negative." (PMID 26943696, 2016).
pancreatic adenocarcinoma (15 papers, 2010 to 2026). "On histopathological examination, the lesion was cytokeratin 7 (CK7)-positive, thyroglobulin-negative, thyroid transcription factor-1(TTF1)-negative and classified as pancreatic adenocarcinoma." (PMID 36010284, 2022).
gastric tumors (13 papers, 2002 to 2025). "Immunohistochemical studies, using anti-cytokeratin 7 and 20 monoclonal antibodies, demonstrated positivity for cytokeratin 7 and negativity for cytokeratin 20 in both pancreatic and gastric tumors." (PMID 36782222, 2023).
chromophobe renal cell carcinoma (12 papers, 2008 to 2025). Chromophobe renal cell carcinoma is a rare subtype of renal cell carcinoma, originating from the intercalating cells of the collecting ducts and macroscopically manifesting as a well-circumscribed, highly lobulated, solid tumor that is usually diagnosed at an early stage. "The main differential diagnosis is metastatic chromophobe renal cell carcinoma, identifiable by large pale cells with prominent cell membranes and perinuclear haloes, but often expressing CK7 (cytokeratin 7) and CD117 (c-kit) immunopositivity." (PMID 39841766, 2025). "For example, chromophobe renal cell carcinoma typically expresses cytokeratin 7 and exhibits characteristic chromosomal losses, whereas renal oncocytomas generally lack these markers." (PMID 40491617, 2025). "Cytokeratin 7 (encoded by KRT7/CK7) is found in the majority of type 1 papillary renal cell carcinomas and chromophobe renal cell carcinomas, and its expression profile alteration is particularly associated with tumorigenesis of primary adenocarcinoma of the small intestine." (PMID 21655371, 2008).
small cell carcinoma (12 papers, 2015 to 2025). A neuroendocrine carcinoma composed of small malignant cells which are often said to resemble "oat cells" under the microscope. "Immunostaining further validated the presence of small cell carcinoma, with stains showing the tumor to be positive for pan-keratin, cytokeratin 20 (CK20), synaptophysin, focally positive for chromogranin and thyroid transcription factor 1 (TTF-1), and negative for cytokeratin 7 (CK7) and GATA-3." (PMID 39651006, 2024).
small cell lung carcinoma (12 papers, 2013 to 2025). Small cell lung cancer (SCLC) is a highly aggressive malignant neoplasm, accounting for 10-15% of lung cancer cases, characterized byrapid growth, and early metastasis. "Other “negative” markers are leucocyte common antigen (LCA) and cytokeratin-7 (CK7) that are positive in lymphoma and small-cell carcinoma of the lung (SCLC), respectively." (PMID 23691324, 2013).
liver cancer (11 papers, 2012 to 2025). An epithelial or non-epithelial malignant neoplasm that arises from the liver. "Moreover, ALB+KRT7+ epithelium‐derived ALD organoids promote the tumour growth by activating Wnt/β‐catenin signalling of liver cancer cells." (PMID 39834100, 2025). "Cytokeratin 7 (CK7) has been identified as a progenitor-cell marker in a rat liver cancer model." (PMID 32433581, 2020). "In liver cancer PROM1 was more strongly co-expressed with a larger number of genes, including CFTR, KRT7, ANXA3, TACSTD2, and FZD1." (PMID 31164716, 2020).
lymphoma (11 papers, 2013 to 2025). A malignant (clonal) proliferation of B- lymphocytes or T- lymphocytes which involves the lymph nodes, bone marrow and/or extranodal sites. "Jurkat T lymphoma cells were used as negative controls with no KRT7 expression since hematological cell lines do not express cytokeratin markers." (PMID 35406395, 2022). "Histologically, we never observed sarcomas or lymphomas arising in electroporated animals and, accordingly, all tumors analyzed expressed molecular hallmarks of human HGSOC, including Cytokeratin-7 (CK7), Wilms Tumor 1 (WT1), Cancer Antigen 125 (CA-125), Paired box 8 (Pax-8), and high Ki67." (PMID 35082152, 2022).
mucinous tumors (11 papers, 2009 to 2026). "The patient was confirmed to have had a borderline mucinous tumour of the right ovary with the tumour cells staining positive for cytokeratin 7 (CK7) and CEA but negative for CA 125 and cytokeratin 20 (CK 20)." (PMID 19154601, 2009).
renal oncocytoma (11 papers, 2009 to 2026). "For renal oncocytoma, there remains some uncertainty as to which features are acceptable for diagnosis, such as how much keratin 7 reactivity, binucleation, atypia, or involvement of structures (vessels or fat) remain compatible with the diagnosis." (PMID 39287823, 2024). "Markers such as cytokeratin 7, parvalbumin or claudin 7 were found to be expressed in the majority of chromophobe RCCs, but rarely in renal oncocytomas." (PMID 19445733, 2009). "While the histological features of LOT of the kidney are similar to those of renal oncocytoma, LOT immunohistochemically expresses keratin 7 (KRT7) but not KIT while renal oncocytoma expresses KIT." (PMID 39980061, 2025).
sarcomatoid carcinoma (11 papers, 2016 to 2025). A malignant epithelial neoplasm characterized by the presence of spindle cells and anaplastic morphologic features. "KRT7 could distinguish the precursor lesions of papillary renal cell tumors, mucinous tubular and spindle cell carcinomas." (PMID 34603393, 2021). "As other immunohistochemical markers were negative, including CD45, CD163, CD68, Desmin, Myogenin, Melanoma, S100, α-SMA, Cytokeratin 7, Cytokeratin 20, MDM2 and CDK4, the tumors were diagnosed as sarcomatoid carcinomas." (PMID 29874846, 2018). "The immunostainings with p63, p40, EMA, and cytokeratin-7 were all negative excluding the diagnosis of sarcomatoid carcinoma." (PMID 27699075, 2016). "The immunostainings with p63, p40, EMA, and cytokeratin-7 were found to be negative excluding the diagnosis of sarcomatoid carcinoma." (PMID 27699075, 2016).
thyroid cancer (11 papers, 2008 to 2024). "The results from the transwell assays demonstrated that the migration of thyroid cancer cells was significantly retarded by inhibiting the expression of KRT7." (PMID 37954148, 2023). "•KRT7 promotes thyroid cancer metastasis through the epithelial-mesenchymal transition and NF-κB signaling pathway." (PMID 37954148, 2023). "KRT7 was consistently differentially expressed in PTC tissues and was associated with inferior clinical characteristics of thyroid cancer patients, as demonstrated by the additional experimental validation." (PMID 37954148, 2023). "In order to gain a comprehensive understanding of the role that KRT7 plays in the progression of thyroid cancer, we conducted a functional study in thyroid cancer cells." (PMID 37954148, 2023). "The result shows that KRT7 may promote thyroid cancer metastasis through the epithelial-mesenchymal transition and NF-κB signaling pathway." (PMID 37954148, 2023). "Due to the fact that KRT7 has been positively stained in almost all thyroid neoplasms while KRT20 has consistently been undetectable, KRT7 and KRT20 are excellent candidates for the thyroid cancer sequencing panel." (PMID 28117295, 2017). "However, there is a lack of specific information regarding the role of KRT7 in thyroid cancer development." (PMID 37954148, 2023). "A second retrospective study examined 153 thyroid carcinoma samples for KRT7/KRT20 immunohistochemically, and they found that all papillary carcinomas, follicular carcinomas, and medullary carcinomas were KRT7 positive and KRT20 negative." (PMID 28117295, 2017).
endometrial carcinoma (10 papers, 2007 to 2025). A malignant tumor arising from the epithelium that lines the cavity of the uterine body. "All endometrial carcinomas with transitional cell differentiation are negative for cytokeratin 20 (CK20), but half are positive for cytokeratin 7 (CK7)." (PMID 17645802, 2007).
endometrioid adenocarcinoma (10 papers, 2013 to 2025). An adenocarcinoma characterized by the presence of malignant glandular epithelial cells resembling endometrial cells. "Endometrioid adenocarcinomas express higher levels of cytokeratin 7 (CK7), PAX8, CA-125, and estrogen receptors." (PMID 30250431, 2018).
intrahepatic cholangiocarcinoma (10 papers, 2012 to 2026). A carcinoma that arises from the intrahepatic bile duct epithelium in any site of the intrahepatic biliary tree. "Cytokeratin 7 (CK7) is almost always positive, Cytokeratin 20 (CK20) can be positive, more often in extrahepatic bile duct carcinoma than intrahepatic cholangiocarcinoma." (PMID 22284391, 2012).
rectal cancer (10 papers, 2012 to 2025). A primary or metastatic malignant neoplasm that affects the rectum. "Immunohistochemical staining indicated that both the rectal lesion and anal fistula were cytokeratin 7 (CK7) (−) and cytokeratin 20 (CK20) (+), and the patient’s condition was diagnosed as implantation of rectal cancer in an anal fistula." (PMID 26943447, 2015). "We performed H&E staining and immunostaining of the proteins cytokeratin 7, cytokeratin 20, and caudal type homeobox 2 transcription factor to confirm that our PDTOs originated from rectal cancer tissue and not from normal rectal mucosa." (PMID 34359661, 2021). "Immunohistochemical staining showed that the specimen was positive for both cytokeratin 20 (CK20) and caudal-type homeobox 2 (CDX2) and negative for cytokeratin-7 (CK7), which indicated that it had originated from rectal cancer." (PMID 28748455, 2017).
renal tumors (10 papers, 2015 to 2025). "However, the lack of immunoreactivity of the kidney tumor sample with thyroid transcription factor 1 (TTF-1) and cytokeratin 7 (CK-7) antibodies did not support pulmonary origin." (PMID 31484545, 2019).
sarcoma (10 papers, 2002 to 2025). A usually aggressive malignant neoplasm of the soft tissue or bone. "To account for the heterogeneity of sarcomas, we employed antibodies targeting three choices of cell surface proteins: cytokeratin 7/8 (CK), pan-cytokeratin (panCK), and a combination of panCK and CSV (panCK + CSV)." (PMID 38811642, 2024).
bladder cancer (9 papers, 2005 to 2025). "In order to evaluate the diagnostic value of KRT7 in bladder cancer, we looked at KRT7 expression in an expanded data set (evaluation data set 2) containing also muscle-invasive T2-4 tumours." (PMID 16265353, 2005). "have exhibited that there is a noticeable rise in the expression of KRT7 mRNA in bladder cancer (BC) in comparison to normal bladder epithelium (NBE)." (PMID 38260844, 2023). "More interestingly, by combining the results of KRT7 expression and hTERT, a sensitivity of 100% was achieved for bladder cancer patients." (PMID 33874920, 2021). "In the present study, we investigated the diagnostic potential of measuring the urinary levels of hTERT, SVV, and KRT7 mRNA for the detection of bladder cancer." (PMID 33874920, 2021). "Even though cancer cells in bladder tumours strongly expresses KRT7 protein, it cannot be used as a new urine marker for bladder cancer within this setup." (PMID 16265353, 2005). "As, Ta tumours showed a high KRT7 expression we examined the potential of KRT7 as a new urine marker for early bladder cancer." (PMID 16265353, 2005). "In addition, we show that keratin 7 is highly expressed in bladder cancer and is correlating to the protein level, can be detected in urine sediments, and has three major molecular isoforms, as determined by Western blotting." (PMID 16265353, 2005). "Furthermore, we showed the presence of high keratin 7 transcript expression in bladder cancer, and Western blotting analysis revealed three major molecular isoforms of keratin 7 in the tissues." (PMID 16265353, 2005). "However, we were able to detect KRT7 protein in urine pellets of some bladder cancer patients." (PMID 16265353, 2005). "In addition, we have shown strong expression of both KRT7 transcript and protein in bladder cancer, the presence of KRT7 protein in urine pellets from bladder cancer patients, and the existence of three major isoforms of this molecule, mainly in malignant cells." (PMID 16265353, 2005). "Prostate-specific antigen (PSA) is an appropriate marker for PCa, and Cytokeratin 7 (CK7) and high-molecular-weight cytokeratin (HMWK) clone‎ ‎34β£12‎‏ ‏ are suitable markers for bladder carcinoma, and their combination can play a significant role in differentiating these cancers." (PMID 33391378, 2021). "We were not able to detect KRT7 protein in either plasma or urine from bladder cancer patients." (PMID 16265353, 2005).
liver fibrosis (9 papers, 2020 to 2024). "The mRNA levels of liver fibrosis markers (Acta2, Col1a1, Col3a1, and Timp1), cholangiocyte proliferation markers (Krt7 and Krt19), inflammation markers (Il6 and Il1b), and the progenitor cell marker (Sox9) were markedly decreased in miR-200c-BDL mice compared to con-BDL mice." (PMID 34880414, 2022). "The validation cohort showed GPC3 was negatively correlated with all liver fibrosis markers ACTA2, COL1A1, COL1A2, COL3A1 and ductular reaction markers KRT7 and KRT19, while SDC4 was positively correlated with ductular reaction index KRT19." (PMID 36816373, 2023). "Transcriptional levels of liver fibrosis markers (ACTA2, COL1A1, COL1A2, COL3A1) and ductular reaction markers (EPCAM, KRT7, KRT19) were significantly upregulated in BA." (PMID 36816373, 2023). "Liver SCTR expression localized in cholangiocytes and correlated positively with liver fibrosis, DR, and transcriptional markers of fibrosis (ACTA2) and cholangiocytes (KRT7, KRT19) both at PE and after SPE." (PMID 35508528, 2022).
mucoepidermoid carcinoma (9 papers, 2013 to 2026). A carcinoma morphologically characterized the presence of cuboidal mucous cells, goblet-like mucous cells, squamoid cells, cystic changes, and a fibrotic stromal formation. "The presence of ‘squamous’ or ‘epidermoid’ areas and clear cells mimicking mucoepidermoid carcinoma can be potentially misleading; however, the absence of mucin, cytokeratin 7 expression and lack of MAML2 rearrangement can help exclude this possibility." (PMID 33351171, 2021).
neuroendocrine tumors (9 papers, 2019 to 2025). "This case corroborates earlier findings that cytokeratin 7 and pancytokeratin are often positive, while markers such as CDX2 and synaptophysin are negative, helping exclude adenocarcinoma and neuroendocrine tumors, respectively." (PMID 39860304, 2025).
pancreatic ductal adenocarcinoma (9 papers, 2010 to 2025). An infiltrating adenocarcinoma that arises from the epithelial cells of the pancreas. "Western blot results showed that, compared to hTERT-HPNE, model genes including KRT7, KRT19, IGF2BP3, and CXCL5, were significantly increased in human pancreatic ductal carcinoma cell lines, PANC-1 and PL45." (PMID 37371833, 2023).